ATXN8OS (ATXN8 opposite strand lncRNA)
Synonyms: KLHL1AS; SCA8; NCRNA00003
Gene: Long non-coding RNA gene on chromosome 13 (70,107,213 to 70,171,738, forward strand). Ensembl gene ENSG00000230223.
Subcellular location: Cytoplasm
Diseases named in the same sentence as ATXN8OS in open-access papers:
ATXN8OS is named in the same sentence as 18 diseases in open-access papers, as found by Europe PMC text mining. Sharing a sentence is not in itself a finding about the gene and the disease. The quoted sentences say what the papers report.
spinocerebellar ataxia type 8 (9 papers, 2009 to 2025). Spinocerebellar ataxia type 8 (SCA8) is a subtype of type I autosomal dominant cerebellar ataxia (ADCA type I) characterized by cerebellar ataxia and cognitive dysfunction in almost three quarters of patients and pyramidal and sensory signs in approximately a third of patients. "Spinocerebellar ataxia type 8 (SCA8) is an autosomal dominant neurodegenerative disease caused by non-coding CTA/CTG repeat expansions in ATXN8OS (ataxin 8 opposite strand)." (PMID 40765612, 2025). "Three patients with PD (1.5%) were found to have heterozygous repeat expansions in ATXN8OS, the gene causative of spinocerebellar ataxia type 8 and is associated with long non-coding RNA." (PMID 40765612, 2025). "Similarly, spinocerebellar ataxia type 8 (SCA8) can be caused by a CTG expansion (NR_002717.2:n.1103CTG[107_127]) in the 3′UTR of ATXN8OS." (PMID 40610610, 2025). "For instance, spinocerebellar ataxia type 8 (SCA8), an autosomal dominant neurodegenerative disease, is caused by CTA/CTG repeat expansion in the ATXN8OS gene." (PMID 33477683, 2021). "The main event in the pathogenesis of spinocerebellar ataxia type 8 is binding of ATXN8OS to alternative splicing factor MBLN1." (PMID 30871545, 2019). "A genetic ataxia panel showed 112 and 29 CTG repeats in the ATXN8OS gene, confirming a diagnosis of spinocerebellar ataxia type 8 (SCA8)." (PMID 41037212, 2025). "Recently, TAU pathology was observed in some cases of spinocerebellar ataxia type 8 (SCA8), a condition caused by abnormal CTA/CTG repeat expansions in ATXN8OS which have also been reported in PSP." (PMID 38554150, 2024). "Spinocerebellar ataxia type 8 (SCA8) involves the expression of an expanded CTG/CAG combined repeats (CR) from opposite strands producing CUG expansion transcripts (ataxin 8 opposite strand, ATXN8OS) and a polyglutamine expansion protein (ataxin 8, ATXN8)." (PMID 19203395, 2009).
spinocerebellar ataxia (5 papers, 2014 to 2024). "For instance, an expanding tri-nucleotide repeat within the ATXN8OS lncRNA locus silences ATXN8OS expression and has been associated with spinocerebellar ataxia and Parkinson disease." (PMID 33329688, 2020). "Among the nine-lncRNAs, lncRNA ATXN8OS participate in spinocerebellar ataxia by affecting the localization and activity of splicing factors and mutations in the ATXN8OS are associated with the amyotrophic lateral sclerosis." (PMID 31001325, 2019). "ATXN8OS is a long ncRNA localized in GABAergic interneurons and plays a significant role in the development of SCA8, a type of ataxia caused by repeat expansion in ATXN8OS and ATXN8." (PMID 24624135, 2014). "P-3 carried 188 repeats of the ATXN8OS gene and suffered tremors for over 40 years but showed no impaired tandem gait or other ataxia signs." (PMID 38961870, 2024).
breast carcinoma (3 papers, 2021 to 2022). "Notably, the lncRNA ATXN8OS was found to be hypermethylated by Rg3 in MCF-7 breast-cancer cells." (PMID 33477683, 2021).
schizophrenia (3 papers, 2012 to 2024). A major psychotic disorder characterized by abnormalities in the perception or expression of reality. "Genome analyses also identified variants with potential clinical implications, including TREs (one in DMPK; two in ATXN8OS) and ultra-rare loss-of-function SNVs in ZMYM2 (a novel candidate gene for schizophrenia)." (PMID 33526774, 2021). "Multiple genes encoded by chromosome 13 have been suggested to contribute to schizophrenia susceptibility, including DAOA, 5-HTR2A, KPNA3 and KPNB3, ESD, ATXN8OS, KFL5, EFNB2, and PCDH8." (PMID 22214315, 2012).
cervical cancer (1 paper, 2025). A primary or metastatic malignant neoplasm involving the cervix. "From this analysis, patients with advanced stages of cervical cancer were associated with the ATXN8OS marker, C5orf60 indicator, and INE1 index gene." (PMID 41300873, 2025).
glioblastoma (1 paper, 2023). The most malignant astrocytic tumor (WHO grade IV). "In glioblastoma cells, another lncRNA, ATXN8 Opposite Strand (ATXN8OS), has been shown to stabilize the GLS2 transcript by recruiting the RNA-binding protein (RBP) ADAR." (PMID 38067269, 2023).
neuroblastoma (1 paper, 2013). Neuroblastoma (NB) is the most common solid, extracranial childhood tumor. "Using antiserum raised against ORF, ATXN8OS ORF expression was detected in various human cells including lymphoblastoid, embryonic kidney 293, neuroblastoma IMR-32, SK-N-SH, SH-SY5Y cells and human muscle tissue." (PMID 24040107, 2013).
cancer (3 papers, 2021 to 2022). A tumor composed of atypical neoplastic, often pleomorphic cells that invade other tissues. "Rg3 induces hypermethylation and downregulation of lncRNA ATXN8OS, while lncRNA ATXN8OS mainly stimulates key oncogenes through sponging miR-424-5p, thus inhibiting cancer cell proliferation." (PMID 35409396, 2022). "Although little is known about its role in cancer development and progression, previous studies indicate that ATXN8OS has oncogenic properties and therefore stimulates cancer-cell growth." (PMID 33477683, 2021). "ATXN8OS was identified as a lncRNA that can be downregulated via promoter hypermethylation by Rg3 in MCF-7 cancer cells." (PMID 33477683, 2021). "The effect of Rg3 on ATXN8OS expression was then examined, and the role of the lncRNA in cancer-cell growth was elucidated." (PMID 33477683, 2021). "Therefore, data on lncRNAs other than ATXN8OS should be obtained to comprehensively explore how Rg3-regulated lncRNAs affect cancer-cell survival or proliferation." (PMID 33477683, 2021). "Moreover, ATXN8OS was found to induce the proliferation of cancer cells and this was suppressed by Rg3." (PMID 33477683, 2021). "Therefore, our findings suggest that Rg3 suppresses MCF-7 cancer-cell proliferation but increases apoptosis by modulating the ATXN8OS/miR-424-5p/target-gene axis." (PMID 33477683, 2021). "The initial category, containing ANKHD1, ATXN8OS, HSPB8, LSM7, MAFB, and TCTN2, is involved in the direct regulation of cancer cell proliferation, apoptosis, and cancerization." (PMID 34235216, 2021).
tumor (2 papers, 2021). "When taken together, Rg3 downregulated ATXN8OS that inhibited the tumor-suppressive miR-424-5p, leading to the downregulation of the oncogenic target genes." (PMID 33477683, 2021). "As shown by qRT-PCR, ATXN8OS expression was significantly reduced in tumor tissues derived from sh-ATXN8OS-transduced MCF-7 cells." (PMID 33385064, 2021). "Moreover, ATXN8OS was found to be overexpressed in BC tissues and cells, and its depletion repressed BC cell proliferation and invasion, highlighting its role as a tumor promoter in BC." (PMID 33385064, 2021). "In contrast, little is known about the role of ATXN8OS in tumor development." (PMID 33477683, 2021). "Specifically, the authors reported that ATXN8OS sequestered the tumor-suppressive miR-204." (PMID 33477683, 2021). "At the molecular level, ATXN8OS sponged a tumor-suppressive miR-424-5p, thereby activating key oncogenes such as EYA1, DACH1, and CHRM3, which could be suppressed by Rg3 treatment." (PMID 33477683, 2021).
ATXN8OS also shares sentences with these, for which no sentence is quoted: amyotrophic lateral sclerosis (2 papers); Ataxia (2); brain disorder (1); dementia (1); essential tremor (1); hereditary cerebellar ataxia (1); myotonic dystrophy type 1 (1); Parkinson disease (1); Tremor (1).